CD4 (CD4 molecule)
Diseases named in the same sentence as CD4 in open-access papers (continued):
Sharing a sentence is not in itself a finding about the gene and the disease.
tumor (continued). "Thus, according to their coreceptor expression, iNKT cells are thought to play different roles in health and disease; for example, liver CD4- iNKT cells are much more effective at mediating tumour rejection compared to their CD4+ counterparts." (PMID 37536148, 2023). "In addition, significant increases in IFN-γ+ CD8+T-cells and CD4+ T-cells populations within tumor-infiltrating lymphocytes (TIL) were observed after MyxV_CD47/IFN-γ treatment." (PMID 37835397, 2023). "Although IL‐6 is incapable of directly inducing the activation and cytokine production of CD8+ T cells, CD8+ T cells were not efficiently primed and activated the anti‐tumor function because of the insufficient helper activity of IL‐6‐sensitized CD4+ T cells, resulting in tumor development." (PMID 37031459, 2023). "However, CD4+ T cells play helper functions through secretion of cytokines that orchestrate the immune response and have a dual role in the tumor microenvironment." (PMID 37529610, 2023). "Further mechanistic studies indicate that combination treatment effectively promotes dendritic cells maturation in lymph nodes, enhances the number and infiltration of CD8+ T and CD4+ T cells in tumor tissue, and improves memory T cell number in spleen, thus activating the antitumor immune response." (PMID 38023716, 2023). "TGF-β is mostly recognized as a tumor-promoting cytokine by inducing cancer cell migration and invasion and as an immunosuppressive factor by inhibiting the generation and effector function of CD4+ and CD8+ effector T cells." (PMID 36860656, 2023). "There is a similar effect of tumor cell clonality on CD4 T cell polarization." (PMID 36980203, 2023). "In our pre-treatment analysis, we identified that responders showed a higher frequency of proliferating CD28-expressing CD8 T cells as well as proliferating CD4 conventional T cells, suggestive of ongoing immunity, potentially encompassing anti-tumour immune responses." (PMID 36818683, 2023). "Furthermore, adenosine-A2AR signaling also promotes the induction of Foxp3+Treg cells from the CD4+Foxp3− T cells that suppress effector T cell-mediated anti-tumor responses, promoting tumor progression." (PMID 37834375, 2023). "From each patient, blood, dissociated liver, and tumor tissues were subjected to Ficoll gradient centrifugation to separate mononuclear immune cells from which memory CD4+ T cells, memory CD8+ T cells, CD56+ NK cells, and CD14+ monocytes/macrophages were sorted to a purity of >98%." (PMID 37388918, 2023). "The results showed that rAd-IL-2 significantly stimulated tumor-specific cytotoxic T lymphocyte responses by inducing the recruitment of CD4+ and CD8+ T cells to tumors, leading to tumor regression and long-term survival of mice during the 120-day treatment period." (PMID 37234162, 2023). "Moreover, a correlation between CD83+ (mature) cDCs and CD4+/CD8+ T-cell infiltration at the invasive margin of the tumor has been observed in immunohistochemical analyses." (PMID 36980187, 2023). "Their results also indicate a possible role of CHST4 in CD4+ T cells, macrophages, dendritic cells and neutrophils recruitment into tumour microenvironment which may lead to inhibition of tumour progression." (PMID 37545696, 2023). "Interestingly, some studies have reported enhanced persistence of tumour-specific CD4+ cells compared to CD8+ cells following antigen stimulation, due to a lowered propensity to activation-induced cell death and bona fide exhaustion." (PMID 37684239, 2023). "These coinhibitory receptors could reduce tumor-specific CD4+ and CD8+ T-cell effector function, impair T-cell functionality, and induce T-cell exhaustion on a systemic level that leads to generalized immune suppression." (PMID 36776832, 2023).
tumor (continued). "However, lncRNA colorectal neoplasia differentially expressed (CRNDE) is highly expressed in multiple cancer types, and in CRC, lncRNA isoform CRNDE-h is transmitted via tumor-exosomes to induce Th17 differentiation in tumor-infiltrating CD4+ T cells." (PMID 37346034, 2023). "Additionally, WFA targets immunosuppressive cell populations including CD11b+Gr1+MDSCs and CD25+CD4+T-regs, reducing their presence in the tumor." (PMID 37370701, 2023). "Finally, we examined TCR sequences from CD4 tumor infiltrating lymphocytes (TIL) in tumors from vaccinated mice and detected TILs with TCR sequences against all the immunizing peptides." (PMID 37880313, 2023). "We then determined whether the increased proportions of CD8+ CD69+ CD44hi and CD4+ CD69+ CD44hi T cells following ex vivo restimulation with viable 4T1 tumor cells would correspond with increased IFN-γ production." (PMID 36839766, 2023). "Graphical Abstract: We identified a novel population of CD4 tumour‐infiltrating lymphocytes (TILs) in BLCA, defined as the co‐expression of PD‐1 and CD200, which may help to explore the mechanisms of tumour progression and immunotherapy resistance." (PMID 37313656, 2023). "TNBC patients with long-term disease-free survival (DFS) have higher human leukocyte antigen DR (HLA-DR) expression than relapsed patients, whereas HLA-DR expression in the epithelial compartment correlates with CD4 and inducible costimulatory expression in the stromal compartment of the same tumor." (PMID 37744276, 2023). "In addition, we also calculated the percentage of TCR + macrophages with shared TCR sequences with Cd4+ (Cd4-share) and Cd8+ T cells (Cd8-share) in the tumor tissue." (PMID 36718369, 2023). "Their role is the presentation of tumor antigens in the brain or cervical lymph nodes to initiate responses by effector T lymphocytes associated with immune defense, such as cytotoxic T lymphocytes (CTL) and CD4+ T lymphocytes." (PMID 37274252, 2023). "Both CD8+ and CD4+ T cell responses are needed for an effective tumor targeting response." (PMID 37215122, 2023). "A smaller population of CD69+CD103+ CD4+ T cells was also apparent within the tumor." (PMID 36689623, 2023). "It has been established in previous study that intratumoral administration of TLR9 agonists may increase OX40 expression on tumor infiltrating CD4+ T helper cells." (PMID 37700338, 2023). "We show that patients with intense CD4+ cell infiltration (>4.6%) or weak CD20+ cell infiltration (<10%), as well as patients with high PD-L1 expression on tumor cells (≥1%), could be characterized by a higher risk of recurrence." (PMID 38067231, 2023). "Finally, we examined TCR sequences in CD4 tumor Infiltrating lymphocytes (TIL) from vaccinated mice and found that the TIL contained TCR sequences specific to the three vaccine peptides." (PMID 37880313, 2023). "Furthermore, CD4+ cells directly kill tumor cells via the secretion of effector molecules, such as cytokines (IFN-γ and TNF-α), upon DC activation." (PMID 38328405, 2023). "While this could fit with our hypothesis of reduced CD8+ T-cells and increased Tregs impacting on anti-tumour immunity, Tregs are only a small, albeit potent, sub-population of predominantly CD4+ T-cells in CRC." (PMID 36980751, 2023). "Increased proportion of CD3+ T cells associated with MDSCs in spleen of tumor‐bearing mice was also observed, but it did not affect the proportions of CD4+ T and CD8+ T cell subsets in CD3+ T cells." (PMID 36373232, 2023). "Here we show, in a human in vitro setting, that only cDC1, but not pDC, cDC2 or moDC can relay CD4+ T-cell help for CTL priming to cell-associated tumor antigens." (PMID 36639382, 2023). "Moreover, VEGFR-2 blockade alone increased the expression of PD-1 in tumor-infiltrating CD4+ cells in an endothelial IFN-γ dependent manner." (PMID 38193080, 2023).
tumor (continued). "Although the CD4+ TILs also remained stable in the combination group, the proliferation of CD4+ T cells, the Th1/Th2 ratio as well as IFNγ+ CD4+ TILs also increased, indicating an increase of tumor-specific CD4+ T cells by the combination treatment." (PMID 37771774, 2023). "Therefore, we analyzed the correlation of QPCTL expression with six kinds of infiltrating immune cells, namely, CD8+ T cells, CD4+ T cells, B cells, dendritic cells, macrophages, and neutrophils, and tumor purity from the TIMER website." (PMID 37063864, 2023). "Additionally, cancer cells can influence memory CD4 T cells to express and release IL-1 in an IL-22-dependent manner, thereby facilitating tumor growth." (PMID 38235128, 2023). "In line with this, Hh pathway inhibitor induced tumor regression and accompanied by recruitment of CD4+ and cytotoxic CD8+ T cells and an upregulation of MHC class I according to IHC analysis of biopsies from patients with BCC, indicating the activation of immune microenvironment." (PMID 37213270, 2023). "C3aR deficiency in mice had a major impact on T-cell-dependent antitumor effector mechanisms, and the frequency of tumor-infiltrating CD4+ T lymphocytes was significantly increased in C3aR-deficient mice to mediate a more robust adaptive immune response against cancer." (PMID 37174113, 2023). "The analysis results were visualized by a heatmap, which showed the significant difference in the composition of tumor-infiltrating immune cells, such as CD8+T cells, memory CD4+T cells, B cells, and cancer-associated fibroblast between the high- and low-risk groups." (PMID 37543760, 2023). "Similarly, CD4+/CD3+ T lymphocytes ratio of HL group was higher in para-tumor tissue than the other two groups (both P < 0.001)." (PMID 37215452, 2023). "Indeed, triggering the CD137 pathway promotes the development of cytotoxic activity in CD8+ T cells and the induction of a Th1 response in CD4 T cells, which boosts effector anti-tumour functions." (PMID 37108276, 2023). "Furthermore, mIF results showed that patients with high levels of GC had high numbers of PD-1+ and CD4+PD-1+ cells in the tumor microenvironment, but the numbers of CD8+PD-1+ cells were comparable in two groups." (PMID 37114049, 2023). "As explained, CD4 + Foxp3 + Tregs are potent immunosuppressive cells that may help tumor progression." (PMID 37221555, 2023). "During tumor progression, large numbers of CD4+ T cells and CD8+ T cells are usually depleted, and studies have demonstrated that during the course of CRLM, the numbers of these two cells are significantly reduced and more CD4+FOXP3+ Tregs are found in liver metastasis." (PMID 38201487, 2023). "Regulatory B cells, CD4+ Th2 cells, bone marrow myeloid-derived suppressor cells (BM-MDSCs), CD4+ T regulatory cells suppressor cells and alternatively activated macrophages (M2) are engulfed by the tumor development." (PMID 37251324, 2023). "However, CD4+ T cells and their secreted factors also play a crucial role in the tumor microenvironment and can orchestrate both pro- and antitumoral immune responses." (PMID 36980536, 2023). "By contrast, the reduction of tumor-infiltrating regulatory T cells (Treg) in the combination groups may partly explain the inconspicuous increase of CD4+ T cells in tumors." (PMID 37771774, 2023). "Herein, we demonstrate that human NSCLC cells, including tumor cell lines and primary tumor cells from clinical patients, efficiently drive the metabolic adaption of human CD4+ T cells, instructing differentiation of regulatory T cells while inhibiting effector T cells." (PMID 38062068, 2023). "Hence, given the imbalance between CD4+ T‐cell subsets, we propose adoptive T‐cell therapy (tumour reactive CD4+ Th‐cell reinfusion), CAR T‐cell therapy and immune checkpoint blockade, such as anti‐CTLA4, to reactivate Th cells and inhibit Treg cells." (PMID 36967539, 2023). "In this research, CD4+ memory T cells take up high contents in the tumor environment." (PMID 37082269, 2023).
tumor (continued). "Moreover, CD4+ T lymphocytes exhibited direct eradication ability of tumor cells by IL2 neutralization 36 which makes targeting CD4+ T lymphocytes a promising therapy for HL-related ICC." (PMID 37215452, 2023). "Increased infiltration of activated memory CD4+ T cells, neutrophils, and M1 macrophages was found in patients with a high RMscore, supporting prior results that these immune cells play an essential function in the microenvironment of the tumor." (PMID 35635121, 2023). "Furthermore, there was increased infiltration of transferred tag-specifric TCR transgenic CD8+ or CD4+ cells with irradiated tumours vs unirradiated tumours." (PMID 37686543, 2023). "At the transcriptome level, it is noteworthy that PNI positivity was negatively correlated with the degree of infiltration of immune killer cells in OC tumor tissues, including macrophage, central memory CD4 T-cell, natural killer cells, monocyte, and central memory CD4 T-cell." (PMID 37799274, 2023). "Tumour cells surrounding clusters of CD11c-Venus+ immune cells with CD4+ T cells upregulated the expression of MHC-II exclusively in mice bearing HCmel12 CRISPR-ctrl tumours, consistent with the notion that CD4+ T cells were activated locally and secreted IFNγ in an antigen-dependent manner." (PMID 37316667, 2023). "Our group found that thalidomide can suppress the regulatory T cells (Tregs), a minor subset of CD4+ T cells (~10%) with unique immunosuppressive activity that have been shown to accumulate in the tumor microenvironment (TME) and represent a major mechanism of tumor immune evasion." (PMID 37111560, 2023). "Furthermore, reduced tumor formation was associated with high expression of CD3, CD4, CD8, and CD11c in the IHC assay (all P < 0.001) and a reduced proportion of MDSCs and Tregs." (PMID 36596856, 2023). "We demonstrated that immune infiltration may play a predominant role in PTC TME and previous researches have reported that immune cells, such as Tregs, dendritic cells and T Cells CD4 memory activated could promote tumor development and metastasis." (PMID 36950012, 2023). "The potential anti-tumor capacity of CD4+ CTLs has been demonstrated across multiple tumor types." (PMID 38077321, 2023). "Moreover, the percentage of CD4 + T cells in the GL261-pirb tumor-bearing mice was significantly lower than that in the GL261-nc tumor-bearing mice." (PMID 36853330, 2023). "Furthermore, RFA has been shown to increase intratumoral T cells, tumor-specific antibodies, and CD4+ and CD8+ cells following ablation." (PMID 37511193, 2023). "The mutation of PTPRD may influence CD4+ T cell infiltration via its phosphatase activity, and promote the occurrence of “hot” TME with enhanced anti-tumor immunity in advanced NSCLC patients." (PMID 37602864, 2023). "As one of the most important players in the tumor microenvironment, tumor-infiltrating lymphocytes consist primarily of CD4 helper cells, CD4 cells, CD25 helper cells, regulatory T cells of the FOXP3 phenotype (Treg), and effector cells such as natural killer cells and CD8+ T cells." (PMID 36936412, 2023). "We next took advantage of two MHC class II-restricted neoantigen-specific TCRs that were isolated from tumor-infiltrating T cells of a melanoma patient, transduced both TCRs into donor CD4+ T cells and expressed the model antigen library in patient-matched immortalized B cells." (PMID 36593398, 2023). "In fact, tumor-infiltrating lymphocytes (TILs), including CD4+ T regulatory cells (Tregs), can create an immunosuppressive environment by promoting immune tolerance to tumor cells and by eliminating members of the innate immune system like natural killer (NK) cells." (PMID 37440925, 2023). "Additionally, although alterations of other immune populations in the tumor microenvironment were observed following DP therapy, such as CD4+ T cells, the detailed regulation mechanism as well as the interplay between distinct immunocytes were undetermined." (PMID 36853831, 2023).
tumor (continued). "This suggests that high DES expression may promote the infiltration of naïve B cells and resting CD4 memory T cells, which exert anti-tumor effects." (PMID 37070095, 2023). "In this trial, apart from the increase in CD4+ and CD8+ T cell proliferation after vaccination, a comparison of tumor specimens before and after treatment revealed an increase in activated, conventional CD4+ TIL in most patients and higher clonality by TCRβ sequencing." (PMID 36992219, 2023). "Using the resource in TIGER, we identified a tumor-enriched subset of CD4+ T cells." (PMID 36049666, 2023). "Furthermore, the immunofluorescence staining results elucidated the successful T cell (CD3-positive) infiltration and the evoking of T helper cells (CD4-positive) in the tumor of mice treated with sono-activated cyaninplatin." (PMID 37343091, 2023). "Indeed, the IBI315‐treated tumor exhibited the highest infiltration of CD3+, CD8+, and CD4+ lymphocytes compared to the control group, parental mAbs groups, or the parental two‐drug combination group in both N87 tumor model and PDX‐1 model." (PMID 37587833, 2023). "Finally, in accordance with clinical evidence, we detected a preponderance of CD4 CAR-T cells in the bone marrow of mice who achieved tumor control, supporting their role in the maintenance of long-term antitumor activity." (PMID 36593069, 2023). "Although the exact mechanism of action of CD4+ T cells remains unclear, their significant antitumor potential can provide new insights into the development of effective tumor immunotherapy." (PMID 37689699, 2023). "This metabolic gene signature resembles that of tumor-infiltrating CD4 Tregs." (PMID 36045586, 2023). "Secondly, we have established a prediction model based on the expression of H3K4me3-related lncRNAs, which could provide a better patient enrollment criteria for tumor immunotherapy targeting CD4+ or CD8+ T cells." (PMID 37131252, 2023). "Interestingly, PD-1 expression in tumor-infiltrating CD4 T cells from SLC43A2 KO tumor-bearing mice was reduced, whereas that in CD8 T cells did not change significantly." (PMID 37147330, 2023). "In addition, we assessed the role of different T-cell subsets in eliminating the tumor cells by depleting either CD4 or CD8 T-cells in the combined-treatment group." (PMID 37654492, 2023). "In addition, the high expression of CDT1 was significantly correlated with lower mast cells, and CD4 T cells expression, which indicated high expression of CDT1 was associated with a pro-tumor environment." (PMID 37790630, 2023). "Additionally, the TIMER database also suggested that RGS1 was positively associated with several tumour‐infiltrating immune cells, including B cells, CD8+ T‐cells, CD4+ T‐cells, macrophages, neutrophils and dendritic cells." (PMID 38081176, 2023). "Notably, apart from CD56 bright natural killer cells and activated CD4 T cells, which were mainly enriched in tumour samples, other immune cell subtypes were mostly enriched in normal samples." (PMID 38045683, 2023). "In addition, immune cells of the tumor microenvironment (CD4, CD8, FoxP3) were to be evaluated for prognostic suitability and a particular focus should be on the prediction of LNM." (PMID 37932810, 2023). "Our current study demonstrates that Uro A treatment can effectively reduce primary tumor burden in a T cell–dependent manner, decrease immunosuppressive tumor-associated macrophages (TAM), and significantly increase the infiltration of CD4+ and CD8+ T cells with a memory-like phenotype in the TME." (PMID 37448553, 2023). "Depleting either CD8+ T cells or CD4+ T cells significantly increased tumor volume in the cells with B7-H3 shRNAs, but to our surprise, depletion of CD4+ T cells increased tumor growth more than depletion of CD8+ T cells, despite similar efficacy of depletion (>99% in both spleens and tumors)." (PMID 36869048, 2023).